HMGB1 (high mobility group box 1)
Diseases named in the same sentence as HMGB1 in open-access papers (continued):
Sharing a sentence is not in itself a finding about the gene and the disease.
brain injury (continued). "Further studies are required to investigate whether astrocyte-derived HMGB1 can induce NS/PCs to differentiate into neurons and to promote functional recovery following brain injury." (PMID 24970310, 2014). "Moreover, we provide evidence on the biomarker potential of HMGB1 and the significance of its nucleocytoplasmic translocation during brain injuries along with the promising neuroprotective effects observed upon HMGB1 inhibition/neutralization in TBI and EBI induced by SAH." (PMID 32610502, 2020). "Similarly, in rodent traumatic brain injury models, anti-HMGB1 monoclonal antibodies may protect against disruption of the blood-brain barrier and reduce HMGB-1 induced inflammation." (PMID 30105229, 2018). "Therefore, HMGB1 is a fundamental DAMP in the hyperacute phase of ischemic brain injury." (PMID 29054968, 2017). "On this basis, this study will investigate the correlation of SBDP145, melatonin, sLOX-1, HMGB1 and HIF-1α in preterm infants suffering from brain injury." (PMID 39256844, 2024). "The independent variables were SBDP145, melatonin, sLOX-1, HMGB1, HIF-1α, and the dependent variable was the prognosis of neonates with brain injury." (PMID 39256844, 2024). "SBDP145, sLOX-1, HMGB1, and HIF-1α levels were found to be significantly elevated in preterm newborns with brain injury." (PMID 39256844, 2024). "Our study aims to assess the significance of SBDP145, melatonin, sLOX-1, HMGB1 and HIF-1α in preterm infants with brain injury." (PMID 39256844, 2024). "The aim of the present study was to identify the impact of the HMGB1 upon NG2+ cells in culture, incorporating study of a validated in vitro model of traumatic brain injury." (PMID 33731757, 2021). "N-3 PUFA supplementation also inhibits microglial activation by inhibiting nuclear translocation and secretion of high-mobility group box 1 (HMGB1) and HMGB1-mediated activation of TLR4/NF-κβ signalling pathways in a model of traumatic brain injury." (PMID 28875399, 2017). "The results of this study showed that after single and multiple factor logistic regression analysis, SBDP145, melatonin, sLOX-1, HMGB1 and HIF-1α could be used as influential factors in assessing the prognosis of neonates with brain injury." (PMID 39256844, 2024). "In this condition, the recruitment of the immune cells to the ischemic zone in association with pathological mediators, such as oxidative stress, excitotoxicity, MMPs, HMGB1, TLR4, arachidonic acid metabolites, and MAPK, might spread ischemic brain injury." (PMID 35986375, 2022). "In an experimental traumatic brain injury study, Omega-3 polyunsaturated fatty acid alleviated the inflammation by modulating microglia polarization through SIRT1-modulated deacetylation of the HMGB1/NF-κB pathway." (PMID 34906140, 2021). "Therefore, HMGB1 constitutively expressed on TLR-4 receptors in adjacent brain, thus up-regulating MMP-9 and expanding neurovascular damage in ischemic brain injury." (PMID 29054968, 2017). "A similar pattern of HMGB1 dynamics was observed in the present EDH model, suggesting that the anti-HMGB1 mAb may be effective in mitigating secondary inflammatory processes across various types of brain injuries." (PMID 38892076, 2024). "Therefore, it is suggested that the role of HMGB-1 and mtDNA in the pathogenesis of PCAS after OHCA, including brain injuries, might be different from those in severe trauma." (PMID 27247778, 2016). "The results of this study showed that the levels of SBDP145, sLOX-1, HMGB1 and HIF-1α in the group of preterm infants with brain injury were higher than that of premature newborns without brain injury, and the level of melatonin was lower than that in the premature infant group (P < 0.05)." (PMID 39256844, 2024).
non-small cell lung carcinoma (39 papers, 2014 to 2025). A group of at least three distinct histological types of lung cancer, including non-small cell squamous cell carcinoma, adenocarcinoma, and large cell carcinoma. "HMGB1 has been implicated not only in various inflammatory diseases but also in cancer development, and overexpression of HMGB1 has been observed in non-small cell lung cancer patients." (PMID 34257627, 2021). "Furthermore, GL disrupts the tumor microenvironment by inhibiting the autophagy-dependent release of HMGB1 from cancer-associated fibroblasts (CAFs), which in turn suppresses NF-κB-driven invasion and metastasis in non-small cell lung cancer models." (PMID 41465435, 2025). "We generated acquired cisplatin resistance of 2 non-small cell lung cancer cell lines (Cis-R) that mimic real clinic situations and tested the outcome of HMGB1 BoxA gene therapy." (PMID 40561066, 2025). "In the study of non-small cell lung cancer, ethyl pyruvate was also found to inhibit the HMGB1/RAGE axis and suppress cell growth through the NF-κB/STAT3 pathway." (PMID 38529373, 2024). "In, 2019, it was reported that ethyl pyruvate (EP) reduces MMP9 levels and attenuates the migration and invasion of non-small cell lung cancer (NSCLC) cells by inhibiting the HMGB1/RAGE axis." (PMID 38529373, 2024). "In non-small cell lung cancer, docetaxel activates NF-κB signalling to stimulate the release of HMGB1 in a ROS-dependent manner and further recruits CD8+ T cells to promote antitumour immunity." (PMID 38906860, 2024). "LINC00680 functions as a sponge of miR-410-3p to enhance high mobility group box 1 (HMGB1) expression to promote the progression of non-small cell lung cancer." (PMID 35800083, 2022). "Altered regulation of nuclear protein HMGB1 has been found in Parkin expressing cells in PD and non-small cell lung cancer cells." (PMID 35153741, 2021). "LncRNA SNHG14 silencing inhibited non-small cell lung cancer progression via miR-34a/HMGB1 axis and promoted NSCLC cell cisplatin sensitivity." (PMID 34234865, 2021). "miR-142-3p overexpression increases the chemosensitivity of non-small-cell lung cancer by inhibiting HMGB1-mediated autophagy." (PMID 32302291, 2020). "They found that miR-449a inhibited cell proliferation, migration, and invasion in non-small cell lung cancer by directly targeting HMGB1." (PMID 31159863, 2019). "Several studies have assessed the diagnostic and prognostic values of high mobility group protein box 1 (HMGB1) expression in non-small cell lung cancer (NSCLC), but these results remain controversial." (PMID 26840258, 2016). "Similarly, in non-small cell lung cancer, downregulation of HMGB1 sensitizes tumor cells to radiation by inhibiting the TLR4/NF-κB signaling axis." (PMID 40969278, 2025). "In non-small cell lung cancer (NSCLC), PLCG2 was correlated with HMGB1 expression and was a biomarker for predicting patient survival and progression." (PMID 39494327, 2024). "Studies have shown that in non-small cell lung cancer (NSCLC), cells undergoing cuproptosis release HMGB1, which subsequently binds to the advanced glycosylation end product-specific receptor (AGER)." (PMID 38778403, 2024). "High mobility group box 1 (HMGB1) has been demonstrated to promote the migration and invasion of non-small cell lung cancer (NSCLC)." (PMID 33807275, 2021). "HMGB1 upregulated NF-κB expression in human pancreatic (BxPC-3), hepatocarcinoma (HUH 7 and H22), fibrosarcoma (HT1080), non-small cell lung cancer (NSCLC), HCC, and breast adenocarcinoma (MCF-7) cells." (PMID 32443845, 2020). "The second study looked for an association between HMGB1 and EGFR mutations in a group including 280 patients with non-small cell lung cancer (NSCLC), some of whom were smokers and others who had never smoked." (PMID 37298365, 2023).
non-small cell lung carcinoma (continued). "While the pre-therapeutic levels of HMGB1 are not predictive or relevant to be used as a prognostic marker for non-small cell lung cancer (NSCLC) patients, its role as a biomarker for prediction of response to therapy has been reported." (PMID 37095543, 2023).
mesothelioma (38 papers, 2013 to 2025). A usually malignant and aggressive neoplasm of the mesothelium which is often associated with exposure to asbestos. "In one investigation, the NSAID aspirin inhibited the carcinogenic effects of HMGB1, an inflammatory molecule implicated in mesothelioma tumor initiation and progression." (PMID 38784478, 2024). "This leads to acetylation of HMGB1, which in turn causes the transfer of HMGB1 to the cytoplasm and to the extracellular space where HMGB1 promotes mesothelioma." (PMID 37880686, 2023). "The importance of the NLRP3 inflammasome and HMGB1 in asbestos-induced inflammation has in addition been linked to mesothelioma." (PMID 25406505, 2014). "Therefore, BAP1 mutations activate the same mechanism—HMGB1 nuclear to cytoplasmic to extracellular release—that promotes asbestos-induced mesothelioma." (PMID 37880686, 2023). "Combined with previous findings, this evidence advises that HMGB1 could be considered as a key inflammatory intermediary involved in the mechanism of carcinogenesis underlying mesothelioma development." (PMID 37626858, 2023). "Mechanistically, asbestos carcinogenesis has been linked to the asbestos-induced release of HMGB1 from the nucleus to the cytoplasm, where HMGB1 promotes autophagy and cell survival, and to the extracellular space where HMGB1 promotes chronic inflammation and mesothelioma growth." (PMID 37880686, 2023). "In this regard, safer HMGB1 inhibitors such as aspirin have been shown to effectively reduce asbestos-induced mesothelioma growth in mice, providing an alternative avenue for clinical translation." (PMID 40559922, 2025). "In the peritoneal cavity, thick, rigid CNTs physically damage mesothelial cells, triggering the release of HMGB1 and promoting mesothelioma development." (PMID 41003038, 2025). "Specifically, loss of BAP1 function reduces the deubiquitylation of HDAC1, which interacts with HMGB1 and BAP1 as a trimer, leading to hyperacetylation and nuclear release of HMGB1, thereby promoting mesothelioma progression." (PMID 40559922, 2025). "Although several biomarkers have been studied for mesothelioma such as mesothelin, fibulin-3, microRNAs (miRNAs), soluble mesothelin-related peptides (SMRPs), and high mobility group box 1 (HMGB1), only a few have shown consistent clinical relevance." (PMID 40807088, 2025). "Aspirin and BoxA, a specific inhibitor of HMGB1, diminished mesothelioma growth in xenograft mice and significantly prolonged the survival of treated animals." (PMID 38784478, 2024). "HMGB1 is actively secreted into the extracellular space during mesothelioma, where it binds to RAGE and TLR receptors to form an autocrine pathway that stimulates the growth, motility, and survival of the cancerous cells." (PMID 38136277, 2023). "Drugs that inhibit HMGB1 directly (such as BoxA or monoclonal antibodies) or indirectly (such as aspirin or ethyl pyruvate) inhibit the growth of mesothelioma in mice and the growth of human mesothelioma cell lines in tissue culture." (PMID 37880686, 2023). "It is hoped that targeting HMGB1 will be a novel therapeutic strategy that benefits mesothelioma patients." (PMID 37880686, 2023). "Possibly because mesotheliomas emerge from an environment rich in HMGB1, mesothelioma cells often actively secrete HMGB1, a process that promotes mesothelioma progression and invasion." (PMID 37880686, 2023). "Whereas HMGB1 is primarily identified in the nucleus of HM, it has also been detected in the cytoplasm and nucleus of mesothelioma." (PMID 38136277, 2023). "HMGB1 overexpression has been observed in several neoplasms, such as breast cancer, pancreatic cancer, melanoma, and mesothelioma." (PMID 37626858, 2023). "Most of our experiments were performed on a mouse mesothelioma model using BoxA, a fragment of HMGB1 that, like CXCL12, engages CXCR4 and induces its internalization together with CD47." (PMID 35565443, 2022).
mesothelioma (continued). "This study reports that BoxA, a fragment of the alarmin HMGB1, induces tumor remission and antitumor immunity in mouse models of mesothelioma and colon carcinoma." (PMID 33956406, 2021). "HMGB1 functions as a ‘master switch’ by which the chronic inflammation that drives mesothelioma growth is initiated and maintained." (PMID 32392897, 2020). "There were 20 mesothelioma patients (24.4%) with fibulin-3 high expression and 41 patients (50%) with HMGB1 high expression." (PMID 33230247, 2020). "Then we sought to characterize the link between fibulin-3 and HMGB1 expression and death outcome of patients with mesothelioma." (PMID 33230247, 2020). "A high level of serum HMGB1 appears to be a sensitive biomarker in diverse disorders, such as mesothelioma, but the different HMGB1 isoforms represent novel biomarker candidates that provide additional mechanistic information." (PMID 32670275, 2020). "MM cell growth, motility, migration, and invasion, as well as EMT signaling, play critical roles in the HMGB1-dependent tumorigenesis and progression of mesothelioma, and ASA inhibits HMGB1, thereby suppressing mesothelioma growth." (PMID 30891101, 2019). "A research group from the USA investigated the effect of HMGB1 targeting by EP on the suppression of the malignant phenotype of human mesothelioma." (PMID 30891101, 2019). "We previously showed that HMGB1 has a key role in mesothelioma pathogenesis, as IT drives MM development and sustains MM progression." (PMID 28186988, 2017). "HMGB1 production in mesothelioma cells in vitro, such as H2052 (epithelioid) and H28 (sarcomatoid), produced higher HMGB1 protein levels than that of a normal human mesothelial cell line." (PMID 28348451, 2017). "One group from the USA provided the first evidence that HMGB1 was highly expressed in both tissues and sera of mesothelioma patients." (PMID 28348451, 2017). "The pivotal role of HMGB1 in asbestos-induced carcinogenesis was first elucidated by researchers, who demonstrated that asbestos exposure induces HMGB1 release, triggering chronic inflammation and promoting mesothelioma development." (PMID 40559922, 2025). "The link between chronic inflammation HMGB1 and mesothelioma, is underscored by the finding that mineral fibers that do not elicit HMGB1 release and thus a sustained chronic inflammatory process, such as palygorskite a mineral fiber abundantly present in in Nevada, are not carcinogenic." (PMID 37880686, 2023). "Cancer may arise when these cells develop survival mechanisms like to those triggered by the HMGB1 pathway in mesothelioma." (PMID 38136277, 2023). "This has led to the hypothesis that developing a specific HMGB1 inhibitor for human use should help patients with mesothelioma." (PMID 37880686, 2023). "Targeting HMGB1 inhibited asbestos carcinogenesis and the growth of mesothelioma." (PMID 37880686, 2023). "One likely factor is the reported role of HMGB1 in the development of mesotheliomas." (PMID 35449069, 2022). "In addition, HMGB1 is a serum marker for mesothelioma in humans, suggesting that HMGB1 is also released from cells in patients with advanced mesothelioma." (PMID 35449069, 2022). "We performed most of our experiments on a mouse mesothelioma model using BoxA, a fragment of HMGB1." (PMID 33956406, 2021). "In addition, serum concentrations of HMGB1 are also significantly higher in mesothelioma patients compared to healthy controls, indicating its significance in tumor development." (PMID 34249695, 2021). "To do so, we used syngeneic BALB/c mice for the Ab1 mesothelioma cells that we injected intraperitoneally (i.p.); Ab1 mesothelioma cells were chosen for this experiment since the in vitro release of DAMPs such as HMGB1 was larger than that obtained from Ab12 cells." (PMID 32120810, 2020).
mesothelioma (continued). "Notably, it has been reported that therapeutic levels of aspirin and its metabolite salicylic acid can suppress growth, migration, invasion, wound healing, and anchorage-independent colony formation of HMGB1-secreting human mesothelioma cells." (PMID 32392897, 2020). "However, HMGB1 concentrations over 450 nM have been detected in the pleural fluid of mesothelioma patients treated with multiple doses of HSV1716 (Joe Conner; Virttu Biologics, personal communication)." (PMID 29543735, 2018). "In addition to its potential role in inflammation and cardiovascular diseases, HMGB1 appears to be involved in drug-induced liver injury, alcoholic liver disease, pancreatic cancer, renal cancer, and mesothelioma." (PMID 27713681, 2016). "However, in drug induced liver disease, alcoholic liver disease, and mesothelioma, the hyperacetylated form of HMGB1 is more important than the unmodified form." (PMID 27713681, 2016). "We evaluated HMGB1 production in four mesothelioma cell lines and a mesothelial cell line by ELISA." (PMID 23617783, 2013). "Biological mechanisms of mesothelioma development can be explored more deeply, and in vitro data can be used to establish a lowest level of exposure for several important biological reactions (e.g., producing elevated HMGB-1 levels in tissues exposed to asbestos fibers)." (PMID 40433487, 2025). "Alternatively, targeting NF-κB may reduce HMGB1 activity and impair mesothelioma growth." (PMID 37880686, 2023). "Notably, mesothelioma tumor cells secrete abundant HMGB1, which may be the ultimate driver of macrophage recruitment inside the tumor." (PMID 35565443, 2022). "Notably, human mesothelioma cells and macrophages upon asbestos exposure release the high mobility group box 1 (HMGB1) protein that is a key player in triggering inflammatory cascade and autophagy, thus directly promoting cell survival and malignant transformation." (PMID 33802313, 2021). "Notably, human mesothelioma cells and macrophages upon asbestos exposure release the high mobility group box 1 (HMGB1) protein that is a key player in triggering inflammatory cascade and autophagy, thus directly promoting mesothelial cells survival and malignant transformation." (PMID 33802313, 2021). "Further studies are in progress to offer an understanding of how asbestos-induced activation of the inflammasome and subsequent generation of biomolecules (IL-1β, IL-18, HMGB1 etc.)may lead to mesothelial cell transformation events and mesothelioma development." (PMID 24885895, 2014). "Since thick, rigid MWCNTs such as MWCNT-7 are cytotoxic to mesothelial cells, and since damaged mesothelial cells release HMGB1, and HMBG1 is involved in the development of mesothelioma, the mechanism of MWCNT-7 induction of mesothelioma is relevant to humans." (PMID 41003038, 2025). "Immunoblotting of cell culture media with an anti-HMGB1 pAb demonstrated that REN and EMMESO mesothelioma cell lines constitutively secrete significant amounts of HMGB1." (PMID 37759736, 2023). "Altogether, this indicates the importance of HMGB1, TNF-α and IL-1β in mediating mesothelioma malignant transformation and progression." (PMID 34249695, 2021). "In this study, we first examined HMGB1 production in MPM cells and found that mesothelioma cells such as H28 (epithelioid) and H2052 (sarcomatoid) produced higher levels of HMGB1 protein than that of human mesothelial cell line MeT-5A." (PMID 23617783, 2013). "Furthermore, it was observed that ethyl pyruvate, which has been identified as an efficient HMGB1 inhibitor and suppressor of RAGE receptor expression, decreased the proliferation of mesothelioma cells both in vitro and in vivo." (PMID 38136277, 2023). "However, the mesotheliomas developed in the visceral pleura and there was no increase in HMGB1 levels in the pleural lavage fluid." (PMID 39940144, 2025). "However, the combination expression of HMGB1 and fibulin-3 was not related to the overall survival of mesothelioma (P = 0.09)." (PMID 33230247, 2020).